GDPGP1 (GDP-D-glucose phosphorylase 1)
Description:
Specific and highly efficient GDP-D-glucose phosphorylase regulating the levels of GDP-D-glucose in cells. Is involved in adaptive response to stress conditions, and plays a key role in neuronal stress resistance by modulating neuronal glycogen levels and maintaining glucose balance (By similarity).
Synonyms: C15orf58; VTC2
Tractability: PROTAC: ubiquitination databases record sites on it; its protein half-life has been measured.
Gene: Protein-coding gene on chromosome 15 (90,233,471 to 90,245,811, forward strand). Ensembl gene ENSG00000183208.
Subcellular location: Cytoplasm
Subcellular location (Human Protein Atlas): Cytosol
Gene Ontology:
Molecular function: GDP-D-glucose phosphorylase activity
Biological process: glucose metabolic process; response to stress
Cellular component: cytoplasm
Genetic constraint (gnomAD): Loss-of-function variants: 20 observed, 22.88 expected, observed/expected ratio (o/e) 0.87, 90% interval 0.61 to 1.27. The upper end of that interval is the gene's LOEUF score, 1.27, which puts it in group 5 of 6, group 1 being the genes least tolerant of losing a copy. Missense variants: 449 observed, 513.46 expected, observed/expected ratio (o/e) 0.87, 90% interval 0.81 to 0.94. Synonymous variants: 219 observed, 219.63 expected, observed/expected ratio (o/e) 1, 90% interval 0.89 to 1.12.
Homologues: Orthologues: chimpanzee GDPGP1 (99% identical), macaque GDPGP1 (96% identical), pig GDPGP1 (84% identical), dog GDPGP1 (82% identical), guinea pig GDPGP1 (81% identical), rat Gdpgp1 (81% identical), rabbit GDPGP1 (80% identical), mouse Gdpgp1 (79% identical), tropical clawed frog gdpgp1 (48% identical), zebrafish gdpgp1 (48% identical), Caenorhabditis elegans mcp-1 (28% identical), Drosophila melanogaster CG3552 (25% identical).
Diseases named in the same sentence as GDPGP1 in open-access papers:
GDPGP1 is named in the same sentence as 2 diseases in open-access papers, as found by Europe PMC text mining. Sharing a sentence is not in itself a finding about the gene and the disease. The quoted sentences say what the papers report.
infection (2 papers, 2017 to 2021). The state of being infected such as from the introduction of a foreign agent such as serum, vaccine, antigenic substance or organism. "Post-infection upregulated 20 transcripts in B-48, including G6PD (6 DEGs), GSDH (3 DEGs), GDPGP1 (4 DEGs), GPI (1 DEG), UGDH (1 DEG), UGPUT (3 DEGs), UGGT (1 DEG) and GPT2 (1 DEG)." (PMID 34948367, 2021).
GDPGP1 also shares sentences with these, for which no sentence is quoted: viral infection (1 paper).